PFKP (phosphofructokinase, platelet)
Diseases named in the same sentence as PFKP in open-access papers (continued):
Sharing a sentence is not in itself a finding about the gene and the disease.
cancer (continued). "Nevertheless, no additional systematic pancancer analyses of PFKP have been performed, which could help us to predict its diagnostic, prognostic, and immunological significance in different cancer types." (PMID 37833332, 2023). "However, no reports have focused on a general summary of the functions of PFKP across cancers." (PMID 37833332, 2023). "PFKP drives glycolysis and promotes CD133+ cancer stem-like cells (CSLCs) that are inherently TA-resistant." (PMID 42024199, 2026). "Cross-cancer comparative analyses further indicate that HCC TANs show unique metabolic programming, characterised by upregulation of glycolytic genes (HK2, PFKP) and fatty acid oxidation genes (carnitine palmitoyltransferase 1A[CPT1A])." (PMID 41451221, 2025). "PFKP is also subject to regulation by HIF-1α at the translational level, promoting cancer cell invasion." (PMID 38982480, 2024). "Moreover, previous data on PFKP have not displayed its diagnostic value for cancer." (PMID 37833332, 2023). "We found that there was a significant positive correlation between PFKP and WNT, VEGF, TGF-β, PI3K, and hypoxia, which are important in cancer development and progression." (PMID 37833332, 2023). "Our data also found that a high level of PFKP was related to worse OS, DSS, DFI, and PFI across cancers." (PMID 37833332, 2023). "Our study established a link between PFKP gene expression and 3-phosphoglycerate in MSI cancers with potential clinical applications." (PMID 36879264, 2023). "Hexokinase II (HKII), platelet-type phosphofructokinase (PFKP), and pyruvate kinase M2 (PKM2) are key rate-limiting enzymes of glycolysis in cancer cells." (PMID 39872359, 2022). "For example, Snail suppresses PFKP to switch the glucose flux toward the pentose phosphate pathway, generating NADPH to facilitate the survival of cancer cells under oxidative stress conditions." (PMID 33980323, 2021). "The PFKP isoform, which was induced in MKL1 ΔN200 cells, frequently prevails over PFKM or PFKL in human cancer cells and in the EMT." (PMID 32699630, 2020). "Glycolysis regulated by three rate-limiting enzymes HK II, PFKP, and PKM2 is usually used by cancer cells to acquire ATP20." (PMID 32801360, 2020). "We have recently shown that Snail increases PPP flux via suppression of PFKP, resulting in NADPH production to potentiate cancer cell survival under metabolic stress." (PMID 32487689, 2020). "Phosphofructokinase, platelet (PFKP), a major isoform of cancer‐specific phosphofructokinase‐1 (PFK‐1) enriched in glycolysis/gluconeogenesis pathway, plays a duel role in cancer cell survival." (PMID 33107155, 2020). "Recent studies in which PFKP expression was indirectly increase or decrease either via the ZBTB7A transcriptional repressor or by sorafenib have suggested that PFKP might be a suitable drug target for anti-cancer therapies as inhibition of PFKP represses aerobic glycolysis." (PMID 29069720, 2017). "Overexpression of PFKP consistently rescued Snail-mediated metabolic reprograming by means of increased glycolytic activity, decreasing NADPH level and cancer cell survival." (PMID 28176759, 2017). "We have shown previously that berberine, an alkaloid isolated from Chinese herbs, interferes with cancer cell metabolism through many different pathways and targets, including but not limited to glycolysis (PKM2, PFKP) and fatty acid synthesis (ACC, ACL)." (PMID 27242914, 2016). "Interestingly, central carbon metabolism in cancer (HK2, MAPK3, MYC, PFKP, PKM2, SLC16A3), galactose metabolism (B4GALT2, HK2, PFKP) and fructose and mannose metabolism (HK2, PFKFB4, PFKP) are associated with metabolism." (PMID 39924557, 2025). "Importantly, we identified that PFKP was a bona fide target of deubiquitinase USP5, and the USP5-mediated deubiquitination and stabilization of PFKP were essential for cancer cell aerobic glycolysis and TNBC progression." (PMID 38217030, 2024).
cancer (continued). "Moreover, GSEA enrichment analysis of RNA-sequencing from data TCGA revealed that Myc signaling pathway was enriched in the PFKP-highly expressed group in HNSCC and various other cancer types." (PMID 38982480, 2024). "Mechanistically, we found that PFKP has both metabolic and non-metabolic roles in cancer progression." (PMID 39664584, 2024). "We further detected the expression of PFKP in TNBC carcinoma and para-carcinoma tissues by immunohistochemistry, and the results showed that the protein expression level of PFKP was higher in carcinoma tissues than that in para-carcinoma tissues in patients with TNBC." (PMID 38217030, 2024). "In addition, to determine the clinical relevance of PFKP-regulated VEGF expression, we analyzed The Cancer Genome Atlas (TCGA) data and revealed that the expression levels of PFKP were positively correlated with VEGF mRNA expression levels in GBMs." (PMID 36435833, 2022). "PFKP mediates the mitochondrial recruitment of AMPK and results in enhanced ACC2 phosphorylation, which facilitates long-chain fatty acid oxidation to maintain energy and redox homeostasis and promote cancer cell survival under GS." (PMID 35641476, 2022). "Eventually, the PFKP/AMPK/ACC2-mediated long-chain fatty acid oxidation facilitates ATP and NDAPH production to alleviate GS-induced metabolic stress, maintain cellular energy and redox homeostasis, and thereafter promote cancer cell survival." (PMID 35641476, 2022). "This non-glycolysis-related function of PFKP provides new opportunities in developing novel therapeutics in cancer." (PMID 35641476, 2022). "Though PFKP is known as a glycolytic enzyme, it has been reported to promote cancer cell proliferation through its non-glycolysis-related functions in regulating YAP/TAZ and PI3K activity." (PMID 35641476, 2022). "Indeed, suppression of PFKP increased the amount of ribulose-5-phosphate (R5P), supporting that PFKP regulates glucose flux into PPP in cancer cells." (PMID 28176759, 2017). "Importantly, suppression of PFKP significantly potentiated cancer cell survival and clonogenic capacity under metabolic stress, and RNAi-resistant PFKP expression vector could successfully attenuate the survival and clonogenic potential of cancer cells induced by shRNA-mediated PFKP knockdown." (PMID 28176759, 2017). "The protein level of PFKP was consistently higher in 18 ccRCC samples compared with their adjacent non-malignant kidney tissues, while PFKM and PFKL proteins show comparable levels between normal and cancer groups." (PMID 27049827, 2016). "Moreover, the knockdown of USP5 significantly reduced TNBC progression through the regulation of PFKP, suggesting that USP5 may serve as a potential therapeutic target for patients with cancer." (PMID 38217030, 2024). "Interestingly, most TCR signaling pathway-related genes had a stronger positive correlation with PFKP in CHOL, which suggested that PFKP may have powerful T-cell immune regulation in this cancer type." (PMID 37833332, 2023). "PFKP also had a strong negative correlation with several cancer drugs." (PMID 37833332, 2023). "Moreover, the ACC2 knock-down in H1299 PFKP KO cells, mimicking the inhibitory phosphorylation of ACC2, significantly enhanced cell viability under GS, suggesting that the inhibition of ACC2 can indeed promote cancer cell survival under GS." (PMID 35641476, 2022). "Although the nondegradative effects of Fbxo7-mediated ubiquitination of PFKP in T cells remain to be elucidated, we hypothesize an essential role for Fbxo7 in cancer cell lines in blood lineages is as an activator of Cdk6." (PMID 35670764, 2022). "However, under glucose-deprived conditions, the pro-EMT transcriptional regulator Snail has been shown to suppress PFKP to shunt glycolytic flux toward the pentose phosphate pathway to generate NADPH; PFKP downregulation under these conditions enhances cancer cell survival and metastasis." (PMID 34367973, 2021).
cancer (continued). "Thus, inhibiting PFK directly in cancer cells is not reasonable since it is also crucial to glycolysis in normal cells, as well as suppression of PFKP reprograms glucose metabolism from aerobic glycolysis towards PPP." (PMID 35006438, 2021). "Genes like PGK1, PFKP, HK2, and LDHA, that are involved in metabolic reprogramming of cancer cells by enhancing glycolysis have a negative correlation with PEBP1/STK11 co-expression." (PMID 40806276, 2025). "Therefore, PFKP, rather than PFKM and PFKL, is thought to be strongly linked to cancer growth, survival, and metastasis, and could be used as a marker for poor prognosis in cancer." (PMID 36276846, 2022).
infection (3 papers, 2016 to 2024). The state of being infected such as from the introduction of a foreign agent such as serum, vaccine, antigenic substance or organism. "In addition, other important checkpoints in glycolysis, namely phosphofructokinase (gene PFKP up-regulated in primary and cytokine activated NK cells at 6 h post-infection) and lactatedehydrogenase (gene LDHA, up-regulated in primary and primed NKC at 3 h and 6 h) were up-regulated." (PMID 27242763, 2016). "Moreover, we also observed an increase in the protein level of PFKP 24-h post-infection, while its mRNA level did not change significantly." (PMID 37796013, 2023).
cardiovascular diseases (2 papers, 2022 to 2025). "This latest research suggests that PFKP has significant potential research value in cardiovascular diseases." (PMID 40385478, 2025). "Both PFKP and lactate are critical contributors to cardiovascular diseases." (PMID 40385478, 2025).
PFKP also shares sentences with these, for which no sentence is quoted: clear cell renal cell carcinoma (3 papers); epidermoid carcinoma (2); glycogen storage disease (2); oral squamous cell carcinoma (2); sarcoma (2); adenocarcinoma (1); Alzheimer disease (1); amyotrophic lateral sclerosis (1); Ascites (1); Cachexia (1); cognitive decline (1); colon adenocarcinoma (1); dengue (1); diabetic kidney disease (1); embryonal carcinoma (1); escherichia coli infection (1); Hypertension (1); invasive ductal carcinoma (1); invasive lobular carcinoma (1); mental illnesses (1); mesothelioma (1); Myocardial fibrosis (1); proteinopathy (1); Salmonella Infections (1); seminoma (1); skin cancer (1); Tarui's disease (1); testis cancer (1); thyroid cancer (1); type 2 diabetes (1).